IL17A (interleukin 17A)
Diseases named in the same sentence as IL17A in open-access papers (continued):
Sharing a sentence is not in itself a finding about the gene and the disease.
Anxiety (continued). "Some of these cytokines performed fundamental functions in CNS: IL-1β in learning and synapse formation, IL-4 in neurogenesis and spatial learning, IL-17A in synaptic plasticity and in the management of anxiety." (PMID 37588589, 2023). "Based on network analyses, we suggest that these cytokines play a key role in linking immune responses in the colon, mesenteric lymph nodes, and serum to hippocampal IL-17A and subsequent anxiety-like behavior." (PMID 35216112, 2022). "Taken together, our results identified IL-17A as a novel biomarker for mediating heightened anxiety in chronic epilepsy." (PMID 35875667, 2022). "Antibodies that decrease the production of IL-17A have also been shown to decrease anxiety-like behaviors." (PMID 35216112, 2022). "Recently, γδ T-cells have been shown to modulate anxiety-like behavior by releasing IL-17a at the meninges and eliciting transcriptional changes in neurons." (PMID 35328680, 2022). "This study also revealed that meningeal γδ T cell-derived IL-17A regulates anxiety-like behaviors of mice." (PMID 35693762, 2022). "In this study, we demonstrated that IL-17A deletion alleviated elevated anxiety in chronic epilepsy, as evaluated by OFT and EPM test." (PMID 35875667, 2022). "In our study, IL-17A gene expression was significantly increased in the hippocampus, which is known to contribute to the development of anxiety." (PMID 35216112, 2022). "γδ T cells are also found in meninges where they secrete the proinflammatory cytokine IL-17a and participate in the development of anxiety-like behavior in mice." (PMID 35773312, 2022). "These inflammatory responses, particularly the inflammatory cytokine IL-17A, are in turn related to hippocampal IL-17A and anxiety-like behavior." (PMID 35216112, 2022). "Epileptic IL-17A WT mice showed thigmotaxis and reluctance to stay in open arms, whereas IL-17A KO mice spent more time in the center area and open arms, suggesting alleviated anxiety in epilepsy." (PMID 35875667, 2022). "Here we identified a novel target, interleukin-17A (IL-17A), which can contribute to TLE-associated anxiety." (PMID 35875667, 2022). "For example, meningeal γδ T cells will increase the expression of IL-17A to modulate anxiety-like behavior after the injection of LPS, indicating the possible link between meningeal γδ T cells and microbiota." (PMID 33868300, 2021). "A recent study identified a cluster of RORγt-positive γδ T cells in the meninges that regulates anxiety-like behavior via IL-17a signaling in neurons." (PMID 33957945, 2021). "IL-17A does not exacerbate neuroinflammation and significantly improves learning and anxiety deficits in this IL-17A overexpressing APP/PS1 mice." (PMID 33132897, 2020). "The low-grade levels of the systemic inflammatory mediators IL-6, IL-12p70 and IL-17A correlated to memory, anxiety, anhedonia and species-typical behavior, indicating a possible influence on behavior." (PMID 25133574, 2014). "In adulthood, IL-17A-imprinted offspring displayed an increase in anxiety-like behavior." (PMID 39384965, 2025). "Similarly, reduced IL-17a production by meningeal γδ17 T cells alleviates anxiety-like behaviors by limiting IL-17a signaling to cortical glutamatergic neurons." (PMID 40821767, 2025). "We concluded that prenatal exposure to IL-17A may lead to anxiety-like behavior under specific experimental settings." (PMID 39384965, 2025). "Furthermore, P2X7 receptor activation modulates the reinforcing and psychomotor effects of METH, possibly via an IL-17A-dependent mechanism, given this cytokine’s emerging role in anxiety regulation." (PMID 40746552, 2025). "Interestingly, TNF-α on D1 and D3, IL-6 on D3, IL-8 on D3 and D7, and IL-17A on D1, D3, and D7 correlated with higher anxiety rate (all P<0.05)." (PMID 37878890, 2023).
Anxiety (continued). "However, delivery of recombinant IL-17a into the CSF of Tcrd−/− mice led to increased anxiety behavior, indicating the role of γδ T cells expressing Il-17a as potent homoeostatic regulators of anxiety." (PMID 37608988, 2023). "Furthermore, anxiety was positively correlated to IL-17A on D1 (P=0.036), D3 (P=0.009), and D7 (P=0.001)." (PMID 37878890, 2023). "SDR increased anxiety-like behaviors, which correlated with serum and hippocampal IL-17A." (PMID 35216112, 2022). "A direct IL-17A signal may promote neurotransmitter release from excitatory presynaptic terminals of mPFC neurons to induce anxiety-like behaviors." (PMID 35693762, 2022). "A network analysis was utilized to determine whether anxiety-like behavior and hippocampal IL-17A were related to inflammatory responses in the periphery, namely in the colon, mesenteric lymph nodes, and serum." (PMID 35216112, 2022). "Taken together, these analyses indicated that colonic iNOS may be protective against extra-colonic inflammation, and that IFNγ in the MLNs may coordinate the gut-brain inflammatory responses that influence anxiety-like behavior as well as systemic IL-17A." (PMID 35216112, 2022). "Taken together, these results suggest that deletion of IL-17A could attenuate anxiety-like behaviors in chronic epilepsy." (PMID 35875667, 2022). "Our data point to hippocampal IL-17A as a key correlate of anxiety-like behavior." (PMID 35216112, 2022). "Further, IL-17a released by meningeal γδ T-cells have also been shown to modulate anxiety-like behavior, and effect that may be mediated by microglia by inducing phagocytosis of neural progenitor cells." (PMID 35328680, 2022). "The low-grade levels of these systemically circulating inflammatory markers were secondly significantly associated with behavior; We found levels of IL-6, IL-12p70 and IL-17A to significantly correlate with memory, anxiety, anhedonia and species-typical behavior." (PMID 25133574, 2014). "Our findings suggest that targeting the embryonic IL-17A pathway during pregnancy may prevent some forms of neurodevelopmental disorders, such as abnormalities in vocalization, anxiety-like and repetitive behavior, which are hallmarks of autism spectrum disorders." (PMID 39384965, 2025). "However, they did not examine the association between IL-17A levels and the degree of anxiety severity." (PMID 38956309, 2024). "For example, a recent study in mice showed that IL-17a secreted from meningeal γδ17 T cells expressing high levels of chemokine receptor 6 regulates anxiety-like behaviour and a recent meta-analysis found that maternal immune activation during pregnancy induces anxiety behaviour in offspring." (PMID 35501893, 2022). "This suggests that inhibiting IL-17A may improve comorbid anxiety in patients with IBD." (PMID 35216112, 2022). "The cellular sources of stressor-induced IL-17A will be further studied in follow-up experiments, but there is already accumulating evidence that brain IL-17A affects behavioral responses; blocking IL-17 effectively attenuates stressor-induced increases in anxiety- and depressive-like behaviors." (PMID 35216112, 2022). "It was originally hypothesized that colonic inflammation would be positively related to anxiety and to hippocampal IL-17A, since we have previously shown that stressor exposure enhances colonic inflammation in mice that are challenged with the colonic pathogen Citrobacter rodentium." (PMID 35216112, 2022). "Salivary IL-17A levels positively correlated with erythrocyte sedimentation rate, anti-streptolysin-O titer, salivary IL-12/23 p40 and matrix metalloproteinase-3 levels, sore and swollen joint counts, BASDAI, chronic TMJ pain and anxiety." (PMID 41751323, 2026). "Given the tight relationship between IL-17A and AngII sensitization, IL-17A also did not correlate with pro-social or anxiety-like behaviors (data not shown)." (PMID 41180499, 2025).
Anxiety (continued). "However, reduced rearing activity, reflecting increased anxiety, was noted in VPA-exposed mice w/o IL-17A treatment compared with controls in both sexes." (PMID 38203599, 2023). "However, a protective role of IL-17A was also indicated in an animal model of AD, and overexpression of IL-17A intracranially could reduce cerebral amyloid angiopathy, improve glucose metabolism, decrease soluble Aβ levels in the hippocampus and CSF, relieve anxiety, and improve learning deficits." (PMID 35459141, 2022). "Th17 (P = 0.003) and IL-17A (P = 0.009) levels were increased in patients with anxiety compared with those without anxiety." (PMID 36386524, 2022). "Importantly, while RSDS-induced blood pressure sensitization appeared tightly linked with systemic IL-17A levels, it was not linked to two major behavioral outputs of the RSDS paradigm (i.e., pro-social and anxiety-like behavior)." (PMID 41180499, 2025). "In our study, IL-17A-imprinted mice exhibited no signs of anxiety-like behavior in the elevated plus maze test, but showed a reduction in buried marbles which could be interpreted as anxious behavior." (PMID 39384965, 2025). "It is shown that after injecting IL-17a antibody into the mPFC of ASD model mice to neutralize IL-17a, the ASD mouse model reproduced the same therapeutic effect as using taVNS, which includes improved anxiety and social function, reduced number of microglia, and inhibited M1 polarization." (PMID 38993386, 2024). "Interestingly, we and others reported no impact of IL-17A on anxiety-like behaviors under physiological conditions, although there was a study showing IL-17A-mediated enhanced alertness." (PMID 35875667, 2022).
Hepatitis (88 papers, 2011 to 2025). Inflammation of the liver. "Some studies demonstrated that elevated level of IL-17A was associated with virus clearance and disease resolution in hepatitis induced by adenovirus or hepatitis C virus (HCV)." (PMID 35144643, 2022). "There is a close association between IL-23 and IL-17A in AILI, APAP induced injury-related liver inflammation via the HMGB-1-TLR4-IL-23-IL-17A axis, in which IL-23 produced by HMGB-1-TLR4-mediated macrophages is required for IL-17A production by γσ T cells." (PMID 36414987, 2022). "Disruption of ATF3 downregulated Foxp3 and upregulated RORγt-mediated IL-17A expression in IR-induced liver inflammation." (PMID 30185770, 2018). "For example, our laboratory showed a much worse Con A-induced hepatitis in IL-17A−/− mice, which differed dramatically from the results published in the US laboratories." (PMID 28243237, 2017). "In experimental hepatitis induced by Listeria monocytogenes infection, IL-17A was shown to increase the neutrophil accumulation in the liver and thus alleviated bacterial burden, paralleling with reduced liver damage." (PMID 24069246, 2013). "Many reports have suggested that the exacerbated liver injury by IL-17A in various hepatitis models can be attributing to its ability to recruit neutrophils." (PMID 24069246, 2013). "IL-17A-deficient mice injected with ConA developed a similar hepatitis as wild-type mice, which suggest that despite IL-17 being increased in T-cell-mediated hepatitis, it is dispensable in this model of liver injury." (PMID 24069246, 2013). "Furthermore, we detected pro-inflammatory cytokines TNF, IL-1β, IL-12p70, IFN-γ, IL-6, IL-2, and IL-17A corresponding with ConA-induced hepatitis and found that pro-inflammatory factors all rise at 6 h after ConA injection." (PMID 36248904, 2022). "Furthermore, the influence of the studied compound on the levels of several other relevant cytokines, such as IL-1β, IL-4, IL-12, and IL-17A, was investigated in mice with ConA-induced hepatitis." (PMID 33919375, 2021). "Protective role, produced IL-17A inhibits the development of hepatitis." (PMID 34211477, 2021). "Our previously study has suggested that Tpl2 critically regulate IL-17A-induced signaling in astrocytes to mediate autoimmune inflammation, here we also demonstrated that Tpl2 is a key modulator in IL-25-induced signaling in hepatocyte to restrain hepatitis." (PMID 31481966, 2019). "In addition, the concentration of plasma IL-17A was significantly higher in the acute phase of HCV infection in patients with self-limiting infection than in those with chronically evolving hepatitis." (PMID 29866105, 2018). "Additionally, IL-17A drives multiple hepatic diseases in murine models, including Con A-induced hepatitis and carbon tetrachloride-induced liver injury." (PMID 26895034, 2016). "In addition, IL-17A is also shown to be involved in many types of human hepatitis, including alcohol induced liver injury and autoimmune hepatitis." (PMID 24069246, 2013). "Moreover, as NK cells are also involved in the pathogenesis of HBV hepatitis, the role of IL-17A in NK cell mediated hepatitis and resultant liver injury remain largely unclear either." (PMID 24069246, 2013). "Since the plasma levels of IL-17A and Th17 cells have been known to be associated with the severity of liver inflammation and/or virological response upon IFN/RBV therapy, we analyzed the potential correlation of the plasma level of IL-17A with the frequency of Th17 cells secreting IL-17A." (PMID 28614389, 2017). "Helper CD4+ T cells play a critical role in the pathogenesis of Con A-induced hepatitis, so we further identified the proportion of liver-infiltrating Th1 (CD4+IFN-γ+) and Th17 (CD4+IL-17A+) subsets." (PMID 37775797, 2023). "In contrast, IL-17RA-/-, IL-17A-/- and IL-17F-/- mice fed MCDD primarily displayed centrilobular, macrovesicular hepatic lipidosis with mild to moderate levels of hepatic inflammation based on H&E staining." (PMID 26895034, 2016).
Hepatitis (continued). "PBMC IL17A mRNA levels in the patients with LC were significantly higher than the patients with CHB, PHC, or severe hepatitis (p < 0.001for all)." (PMID 23448394, 2013). "CD4+ T cell is important for Con A-induced hepatitis, the proportions of pro-inflammatory CD4+ T cell subsets in splenocytes were further analyzed by flow cytometry, including Th1 (CD4+IFN-γ+) and Th17 (CD4+IL-17A+) cells." (PMID 37775797, 2023). "The levels of several other inflammatory mediators, i.e., IL-1β, IL-4, IL-10, IL-12, and IL-17A, were measured in the serum of mice with ConA-induced hepatitis in the presence and absence of GRMS-55." (PMID 33919375, 2021). "Furthermore, the pro-inflammatory effect of the IL-10/IL-17A ratio was observed in patients with advanced MASLD in comparison with those without liver inflammation." (PMID 40918132, 2025). "Importantly, IL-17 source was mostly from ILC3s because Ad-induced hepatitis in ﻿γδ−/− (TCRδ−/−) mice did not affect early IL-17A production or Th1/cytotoxic T-lymphocyte responses." (PMID 34659248, 2021).
osteoporosis (88 papers, 2012 to 2025). A condition of reduced bone mass, with decreased cortical thickness and a decrease in the number and size of the trabeculae of cancellous bone (but normal chemical composition), resulting in increased fracture incidence. "IL-17A is also a vital mediator of bone absorption in inflammatory diseases associated with osteoporosis, and elevated serum concentrations of IL-17A have been observed in patients with postmenopausal osteoporosis." (PMID 35187034, 2022). "Osteoporosis is associated with increased osteoclastogenesis, and IL-17A promotes OCL differentiation by inducing secretion of RANKL." (PMID 32231224, 2020). "Ovariectomy (OVX) can be used as a model to study bone loss induced by estrogen deficiency and the role of IL-17A in osteoporosis development has previously been investigated using various methods to inhibit IL-17A signaling in this model." (PMID 32231224, 2020). "In the current study, we aimed to investigate the possible pathogenic role of IL-17A and IL-10 bone-protecting role in osteoporosis." (PMID 27999647, 2016). "To investigate the possible pathogenic role of IL-17A in osteoporosis, we determined the serum levels of this cytokine in osteoporotic and normal control groups." (PMID 27999647, 2016). "Conversely, in osteoporosis induced by chronic obstructive pulmonary disease (COPD) and parathyroid hormone (PTH), a deficiency in IL-17A reduces bone loss by decreasing osteoclast activity and RANKL expression." (PMID 40248692, 2025). "While IL-17A monoclonal antibodies show promise in improving inflammatory osteoporosis, their long-term efficacy and safety require further investigation to fully establish their clinical value and optimize treatment strategies." (PMID 40873591, 2025). "Both TNF and IL-17A have been found to promote osteoclastogenesis and activate osteoclasts, leading to osteoporosis." (PMID 39974592, 2024). "Postmenopausal women with osteoporosis have higher concentrations of serum IL-17A, RANKL, and OPG and more IL-17-producing CD4+ T-cells in the peripheral blood." (PMID 37958752, 2023). "These immune alterations are likely relevant to other IL-17A-mediated diseases in the postmenopausal state, such as myocardial infarctions and osteoporosis." (PMID 36899902, 2023). "Both in vivo induction by low dose pulsed RANKL (pRANKL) and adoptive transfer of ex vivo generated TcREG suppressed bone resorption, TNFα and IL-17A levels and promoted bone formation to ameliorate osteoporosis in OVX mice." (PMID 34276675, 2021). "In postmenopausal women with osteoporosis, the concentration of serum IL-17A is negatively correlated with BMD, but is positively correlated with sRANKL level." (PMID 33613566, 2020). "While some publications reported IL-17A as a mediator of OVX-induced osteoporosis, others found a bone-protective role for IL-17 receptor signaling." (PMID 32231224, 2020). "Post-menopausal women suffering from osteoporosis have also been shown to have elevated serum concentrations of IL-17A, which correlates negatively with BMD13." (PMID 32231224, 2020). "Analytic results showed that, even lacking significance, there was a trend of associations between subcutaneous nodules and the IL-17A*A/A genotype; and osteoporosis with the IL-17A*G/G genotype." (PMID 29584788, 2018). "It is hypothesized that salivary levels of AGE and IL-17A are high and periodontal and peri-implant clinicoradiographic signs are worse in diabetic patients with osteoporosis and smokers with impaired BMD." (PMID 36424586, 2022). "A study has hypothesized that there are more TNF-α and IL‐17A producing memory T cells in postmenopausal women with osteoporosis." (PMID 36341399, 2022). "At present, there are few studies on the correlation between IL-17A and osteoporosis." (PMID 35371044, 2022). "In vivo study shows that although IL-17A is not required for normal bone homeostasis, it plays a vital role in bone loss of ovariectomized osteoporosis mouse models." (PMID 33408628, 2020).